HIF1A (hypoxia inducible factor 1 subunit alpha)
Diseases named in the same sentence as HIF1A in open-access papers (continued):
Sharing a sentence is not in itself a finding about the gene and the disease.
tumor (continued). "Moreover, HIF-1α signaling is involved in the recruitment and differentiation of MDSCs into tumor-promoting M2 TAMs as well as the recruitment of immunosuppressive Tregs into the TME." (PMID 37345116, 2023). "Used as an inhibitor of HIF-1α, PX-478 is a small-molecule compound with anti-tumor activity." (PMID 36795696, 2023). "SIRT3 in hypoxic environments may affect tumor cell proliferation, invasion, migration, and inflammation levels via the ROS-FPR1/HIF-1α axis, thereby inhibiting tumor cell development." (PMID 37747648, 2023). "This suggests that activation of the transcription factor HIF-1α may play a role in tumor progression." (PMID 37046623, 2023). "Our study implies that patients with high expression of HIF-1α might benefit from approaches to overcome or reverse tumour hypoxia to enhance radiosensitivity." (PMID 37029804, 2023). "HIF-1α, as the most extensively studied aerobic glycolysis regulatory molecule, is overexpressed in many cancers and is the main transcription factor that initiates aerobic glycolysis, controlling cell metabolism to promote tumour growth." (PMID 38052785, 2023). "In addition, we also examined the effect of HIF-1α on anti-tumor metastasis and angiogenesis pathways at the cellular level." (PMID 37239383, 2023). "Moreover, overexpression of HIF-1α prevents the maturity of DCs and reduces the tumor-killing ability of effector T cells, induces the differentiation of regulatory T cells, and accelerates T cell exhaustion." (PMID 37892972, 2023). "Finally, the levels of 27 biologically relevant cytokines were measured in tumor tissue of Group 1 and correlated with HIF-1α tumor tissue levels." (PMID 38273861, 2023). "Some AC samples had nuclear HIF-1α staining in their tumor cells; however, the staining was weak." (PMID 37445752, 2023). "Recently, alkaline degradation products produced by biodegradable magnesium alloys or magnesium oxide (MgO) nanoparticles have been reported to effectively neutralize acidic tumor microenvironment, and improve hypoxia in tumor region by inhibiting hypoxia inducible factor-1α (HIF-1α) pathway." (PMID 37925456, 2023). "HIF-1α activates HIF-1β to form a transcription factor complex, which regulates the expression of multiple genes such as vascular endothelial growth factor and glucose transporter, which are closely associated with angiogenesis and tumor growth." (PMID 37251681, 2023). "The ability of CO2 to increase blood flow could increase oxygenation of the tumor core, decreasing HIF-1α levels and reducing inflammation." (PMID 36982254, 2023). "The activation of STAT3 mediated by HE4 promotes transcription of pro-angiogenic factors such as IL-8 and HIF1α: IL-8 leads to persistent neutrophil recruitment in tumor tissue stimulating neoangiogenesis whereas HE4-HIF1α interaction has to be better characterized yet." (PMID 37445657, 2023). "Endogenous fibroblasts overexpressing HIF-1α can promote tumor growth both in vivo and in vitro." (PMID 36906534, 2023). "Next, we investigated whether Erk1/2/HIF-1α/STAT3/VEGFA is critical for tumor angiogenesis under DOKD feeding." (PMID 37239383, 2023). "In this respect, tipifarnib is speculated to have several mechanisms of anti-tumor effects, and it is superior to previous HIF-1α inhibitors, such as YC-1 and andrographolide." (PMID 37511305, 2023). "The expression of both HIF1α and ObRs is higher in the advanced stages of tumor development." (PMID 37686525, 2023). "Furthermore, extracellular signal-regulated kinase (ERK) signaling was found to regulate HIF-1α expression and tumor growth in hyperthermic non-small-cell lung cancer both in vitro and in vivo." (PMID 37626752, 2023). "Moreover, HIF-1α is an important regulator of tumor cell metabolism, acting mainly on glucose catabolism, and favoring the development of an acidosic environment, stimulating fatty acid synthesis and glycogen synthesis (Warburg effect)." (PMID 37374319, 2023).
tumor (continued). "HIF-1a is a key molecule in the adaptation of tumour cells to hypoxic environments." (PMID 37821935, 2023). "In addition, the presence of the TLR4 receptor has been positively correlated with the hypoxia state of the tumor microenvironment and the expression of the hypoxia-inducible factor-1α (HIF-1α) in CC." (PMID 36831674, 2023). "Tumor-promoting function of NPAS2 is dependent on HIF-1A activation and the engagement of glycolysis-related genes, indicating that NPAS2 may serve as an important therapeutic target to normalize glucose metabolic aberrations responsible for PCa progression." (PMID 36978001, 2023). "Hypoxia conditions in the tumor microenvironment are reflected in HIF1α and LDHA expression." (PMID 36900270, 2023). "Therefore, we aimed to determine the impact of HIF‐1α expression on NK cell effector function and immunosurveillance of metastatic tumor cells in vivo." (PMID 36987917, 2023). "Moreover, c-Myc can post-transcriptionally promote HIF1α expression and further promote tumor growth." (PMID 38173713, 2023). "The increase in tumor size is accompanied by hypoxia which stimulates the expression of pro-angiogenic factors and inhibits the expression or production of anti-angiogenic factors, thanks to the stabilization of hypoxia-inducible factor 1-alpha (HIF1α)." (PMID 37205307, 2023). "Importantly, we demonstrate that HIF1A is a critical factor enabling tumor cell survival in response to ADT and that genetic or pharmacological inhibition of HIF1A sensitizes Pten‐deficient lesions to castration, and leads to durable therapeutic responses." (PMID 37070472, 2023). "HIF‐1α has been regarded as a promoter for tumor development and tumorigenesis." (PMID 36971046, 2023). "The protein participates in processes the ensure the survival of cells under hypoxia, and it has been shown that HIF1A may play a role in the development of tumor resistance to immunotherapy." (PMID 36816977, 2023). "Tumor hypoxia could induce aerobic glycolysis, in which hypoxia-inducing factor-1α (HIF-1α) plays a significant role." (PMID 37476196, 2023). "Two studies support this hypothesis, indicating a mounting body of evidence that suggests inhibition of HIF1α-dependent tumor growth by ascorbate." (PMID 38274206, 2023). "Notch has been found to interact with HIF1α, leading to hypoxia-induced growth of tumor cells." (PMID 37240338, 2023). "Moreover, HIF-1α also induces tumor dissemination to distal cites by directly activating TWIST, CXCR-4, and uPAR." (PMID 36891273, 2023). "So, cells that lack adequate amounts of ascorbate can have increased HIF1α function, which may potentially play a role in tumor progression." (PMID 38274206, 2023). "Tumor tissue of MB-proficient and MB-deficient PyMT/MB mice failed to reveal any positive staining for HIF1α and HIF2α staining." (PMID 37161046, 2023). "This tumor-suppressive effect is mediated by targeting HIF-1α." (PMID 38139352, 2023). "For example, 1 study using N-acetyl cysteine found that this antioxidant suppressed tumor growth in mice by inhibiting the oxidant signals that contribute to HIF-1α stabilization but others have reported that antioxidants accelerate tumor initiation, growth and metastatic potential." (PMID 36935009, 2023). "Taken together, HIF1A expression exhibited negative correlations with anti-tumor immunity and presented a positive association with tumor-suppressive immunity." (PMID 36994412, 2023). "YFSJ can reduce the level of inflammation in the tumor microenvironment in vivo, inhibit the abnormal activation of the Stat3/HIF-1α/BNIP3 signaling pathway induced by tumor-related inflammation, thereby inhibiting the overactivation of mitophagy in skeletal muscle, and finally alleviate CRF." (PMID 36814560, 2023). "In addition, in tumor and stem cells, succinate induces HIF-1α to reprogram energy metabolism under hypoxic conditions." (PMID 38074679, 2023).
tumor (continued). "HIF-1α inhibits immune cells tumor killing function, which is mediated by regulatory cytokines, granulocyte macrophage colony-stimulating factor (GM-CSF), colony stimulating factor-1 (CSF-1), transforming growth factor-β (TGF-β), CC-chemokine ligand 5 (CCL5), and VEGF in TNBC." (PMID 37492478, 2023). "The relationship between HIF-1α and age could be influenced by various factors, including tumor stage, grade, and other molecular features." (PMID 38053655, 2023). "In addition, inhibition of HIF1α can retard tumor development in a murine U251-xenograft model of GBM." (PMID 37382594, 2023). "The transcription factors NF-κB and HIF-1α are frequently activated in tumors, involved in tumor growth and progression, and resistant to chemotherapy through their ability to up-regulate the expression of tumor-promoting cytokines and survival genes." (PMID 36678795, 2023). "However, in a hypoxic environment, vascular endothelial growth factor and HIF-1α are activated in tumor cells, increasing tumor neovascularization and the likelihood of metastasis." (PMID 38274225, 2023). "Finally, in view of the role of hypoxia and hypoxia inducible factor-1α (HIF-1α) in cell function, it was noted that this protein was required for IL-15R to suppress tumor cell CX3CL1 expression." (PMID 37296860, 2023). "In addition, quercetin induces tumor cell apoptosis, autophagy and reduces tumor cell viability mainly by reducing the stability of β-Catenin and HIF-1α, activating the expression of caspase 3 and inhibiting the phosphorylation of Akt, mTOR and ERK." (PMID 37685158, 2023). "Hence, more work is needed to determine the contributions of mitophagy and HIF-1α stability to PRKN’s tumor suppressor function." (PMID 37190124, 2023). "Therefore, it is important to investigate the molecular mechanisms associated with hypoxia in the HCC microenvironment, and the hypoxia-induced factor (HIF) is the main tumor-adapted transcription factor, consisting of HIF-1α, 2α, and 3α." (PMID 37240068, 2023). "Moreover, PKA/CREB signaling-induced M2-like TAMs polarization was deemed to be promoted by tumor-derived lactate, which was directly associated with intercellular Zeb1 expression and the PI3K/Akt/HIF-1α activation." (PMID 37828561, 2023). "Moreover, these core genes (Pik3r1, Akt1, Myc, Egfr, Hif1a, Vegfr, Jun, and Stat3) are closely related to the tumor immune microenvironment, exclusively T cell immune function." (PMID 37799727, 2023). "determine the relationship between HIF-1α and cytokines in tumor tissue, and 4)." (PMID 38273861, 2023). "These agents may be aimed at targeting tumour hypoxia (e.g., targeting HIF1α pathways) or cell signalling pathways." (PMID 37894379, 2023). "In addition, it was known that the phosphorylation of Akt1 and STAT3 regulates the transcription of HIF-1α, a core molecule that induces tumor angiogenesis." (PMID 36647454, 2023). "Under experimentally controlled hypoxia where the induction of HIF-1α was confirmed, we showed in our in vitro investigation that [64Cu][Cu(ES)] accumulates in tumor cells, and that the uptake of Cu-64 significantly increases compared to normoxic tumor cells treated with [64Cu][Cu(ES)]." (PMID 37382663, 2023). "Furthermore, the concentration of HIF-1α in the tumor showed a significant positive correlation with CCL3 and IL-1β (p (R2) 0.007 (0.47); p (R2) 0.011 (0.38)." (PMID 38273861, 2023). "Importantly, the combined inhibition of Smad3 palmitoylation (by using 2‐BP) and hypoxia inducible factor 1 subunit alpha (HIF‐1α) successfully inhibited tumor growth and increased survival rates in mice with xenografts." (PMID 36018061, 2023). "Low NO flux, similar to that generated by constitutive NOSs, maintains cellular homeostasis, drives cell cycle progression, promotes proliferation, neovascularization, angiogenesis, tumour growth and spread, processes governed by the activation of the HIF1α and VEGF signalling pathways." (PMID 38136342, 2023).
tumor (continued). "The lack of association with clinicopathological parameters except tumor size could be the result of assessing HIF-1α staining in a single section from a biopsy, which can provide only a snapshot of the whole dynamic hypoxia environment within the tumor." (PMID 36766555, 2023). "By polarizing TAM to M2-like phenotype in the TME through a process that depends on HIF-1α, lactate generated by tumor cells may accelerate the development of cancer." (PMID 36831413, 2023). "This strategy may prevent the induction of HIF-1α by antiangiogenic agents and potentiate the anti-tumor action." (PMID 36846589, 2023). "However, persistent anti-VEGF therapy leads to hypoxia-inducible factor-1α (HIF-1α) upregulation, which eventually leads to the development of tumor hypoxia and drug resistance." (PMID 37111692, 2023). "In MCC tissue samples, HIF-1α is predominantly expressed at the invading edge of the tumor margin." (PMID 36901857, 2023). "Thus, facilitating DOX and siRNA co-delivery via hypoxia-responsive size-contracting nano-repair to enhance deep DOX penetration into tumours and inhibit HIF-1α expression is an emerging strategy that interferes with hypoxia-induced cancer development." (PMID 37514114, 2023). "Moreover, vascular endothelial growth factor (VEGF) promotes tumor cell growth and is one of the main factors involved in angiogenesis in cancer, induced by hypoxia through HIF1α." (PMID 36253663, 2023). "Furthermore, MDM-B expressed a transcriptome that included enrichment for HIF1a signaling, glycolysis, and the tumor microenvironment, which is known to be pro-angiogenic." (PMID 37858232, 2023). "Furthermore, mTOR enhances the translation of HIF1α, the master oxygen sensing molecule, which fosters multiple tumor-promoting mechanisms such as angiogenesis, metastasis, cell proliferation and glucose metabolism." (PMID 37786827, 2023). "In addition, the hypoxia transcription factor HIF-1a subdomain can be incorporated in a CAR construct to reduce on-target off-tumor toxicity, ensuring CAR T cells activation only under the hypoxic conditions characteristic of the TME." (PMID 37025994, 2023). "Collectively, XIST levels in serum may be used as a tumor marker for TC promoted by HIF-1a, which could be treated using artemisinin." (PMID 37036874, 2023). "Indeed, we observed that tumor-infiltrating HIF-1αΔNφ neutrophils produced higher levels of intracellular ROS compared to HIF-1α-sufficient neutrophils." (PMID 36614196, 2023). "further found that high expression of HSP70 and HIF-1α could be found in the residual tumor cells around the ablation site." (PMID 36712497, 2023). "Moreover, the recent studies have shown a correlation between the expression of HIF-1α in tumors and the presence of cytokines in the tumor microenvironment." (PMID 37501379, 2023). "Interestingly, ST6GAL1 has been shown to protect tumor cells from hypoxic stress by increasing the expression of hypoxia-inducible factor alpha (HIF-1α)." (PMID 38067186, 2023). "Additionally, HIF-1α disrupts the expression of enzymes involved in collagen polymerization and alignment as well as integrin activity, facilitating tumor migration." (PMID 37819576, 2023). "Activation of HIF1α signaling, which is usually triggered in tumor cells under hypoxic conditions, increases tumor cell survival and may contribute to taxane resistance." (PMID 38065937, 2023).
tumor (continued). "The rationale behind this correlation is that as people age, there may be cumulative cellular damage and alterations in the tumor microenvironment, including hypoxia, which could lead to increased HIF-1α expression." (PMID 38053655, 2023). "Inhibition of HIF1α can release the anti-tumor activity of NK cells." (PMID 37790761, 2023). "Hypoxia can induce the expression of HIF-1α in response to hypoxia in the cellular microenvironment, and when hypoxia reaches a critical level, it will cause tumor cell necrosis, but usually, the area of necrosis does not exceed 30%." (PMID 37114130, 2023). "Recently, a preclinical study with a xenograft model of colon cancer in mice showed that BOLD was positively correlated with HIF-1α, indicating that T2*-weighted sequences might be predictive of tumor hypoxia." (PMID 36844199, 2023). "However, its involvement in the pathological processes of this tumor is supported by the fact that the normal kidney tissue of both groups we studied contained significantly different amounts of HIF-1α than tumor tissue." (PMID 38273861, 2023). "Other than hypoxia, pro-tumorigenic pathways and defective tumor suppressors may lead to the upregulation of HIF-1α." (PMID 36846589, 2023). "Thus, to understand if Hif-1α regulates the expression of these metabolic genes, we used two distinct siRNAs targeting HIF1A mRNA to knock it down in BRAF-mutated tumour cells." (PMID 37198319, 2023). "Moreover, miR-22 treatment effectively silenced hypoxia-inducible factor 1 (HIF1α) and enhanced RA signaling in both hepatocytes and T cells, which improved metabolism and anti-tumor immunity." (PMID 37143325, 2023). "Moreover, Tα1 has been shown to promote apoptosis in MDSCs not only by decreasing the Bcl-2/BAX ratio, but also by downregulating HIF-1α in tumor cells to inhibit blood VEGF production." (PMID 37598158, 2023). "Therefore, CAFs would mediate tumor immunosuppression by regulating hypoxia-pseudohypoxia-mediated HIF1α activation via IL-6." (PMID 36764954, 2023). "Intratumoural hypoxia promotes hypoxia-inducible factor 1 alpha (HIF-1α)-mediated metabolic reprogramming by tumour cells, resulting in a shift toward increased glycolysis and altered oxidative phosphorylation in a bid to meet energy and biosynthetic demands in a low oxygen environment." (PMID 38099193, 2023). "Interestingly, the role of autophagy in tumor cell survival is not only restricted to the tumor vicinity, while hypoxia inducible factor-1α (HIF-1α) induced autophagy also plays an important role in metastasis." (PMID 37259445, 2023). "The results revealed that the triple-drug combination markedly inhibited the protein expression of VEGF, VEGFR, PI3K, p-AKT, PDK, p-mTOR, Nrf2 and HIF-1α when compared to that of tumor-control (p < 0.001); while it significantly enhanced the expression of PTEN." (PMID 37025487, 2023). "A number of studies have highlighted the role of aspirin in glucose metabolism, proposing that its effect is mediated through HIF-1α, which may contribute to its anti-tumour activity." (PMID 37720350, 2023). "From the available data it emerges that HIF-1α activation may contribute to tumour development by stimulating cell proliferation, metabolic changes, angiogenesis, cancer invasion, and metastasis." (PMID 36691794, 2023). "This apparent discrepancy between the role of VEGF in cancer biology and its utility as an indicator of cancer aggressiveness needs to be clarified in future studies, so that the implications of IH associated with OSA in the expression of HIF-1α and VEGF at the tumor level can be better understood." (PMID 36831404, 2023). "It is thought that HIF-1α activation, which is a common feature of tumour cells, is more pronounced especially in aggressive tumours and may be an independent marker of poor prognosis." (PMID 37841777, 2023). "ELISA was used to measure the levels of HIF-1α in the tumor and healthy kidney tissue." (PMID 38273861, 2023).